LNMICC (lncRNA associated with lymph node metastasis in cervical cancer)
Gene: Long non-coding RNA gene on chromosome 8 (81,252,601 to 81,281,446, reverse strand). Ensembl gene ENSG00000254027.
Diseases named in the same sentence as LNMICC in open-access papers:
LNMICC is named in the same sentence as 2 diseases in open-access papers, as found by Europe PMC text mining. Sharing a sentence is not in itself a finding about the gene and the disease. The quoted sentences say what the papers report.
cervical cancer (4 papers, 2020 to 2024). A primary or metastatic malignant neoplasm involving the cervix. "LNMICC (lncRNA associated with lymph node metastasis in cervical cancer) which promoted lymph node metastasis by reprogramming fatty acid metabolism acted as a candidate prognostic biomarker and therapeutic target in cervical cancer." (PMID 38355626, 2024). "In primary cervical cancer lymph node metastasis, LNMICC significant downregulation of acetyl-CoA carboxylase 1 (ACC1), FASN in the deregulation of FA metabolism, and miR-190 exert inhibitory effects on LNMICC expression by directly binding to LNMICC." (PMID 36452489, 2022).
LNMICC also shares sentences with these, for which no sentence is quoted: lymph node metastasis (2 papers).